FADS1 (fatty acid desaturase 1)
Diseases named in the same sentence as FADS1 in open-access papers (continued):
Sharing a sentence is not in itself a finding about the gene and the disease.
vitiligo (2 papers, 2019 to 2025). Generalized well circumscribed patches of leukoderma that are generally distributed over symmetric body locations and is due to autoimmune destruction of melanocytes. "Among the DEGs identified in vitiligo specimens was FADS1, which encodes a fatty acid desaturase that catalyzes the final step in the formation of EPA and ARA from PUFAs." (PMID 31866583, 2019). "However, in vivo data are needed to validate the results of this study and confirm the role of FADS1 deficiency in vitiligo patients." (PMID 31866583, 2019). "The SMR analyses and colocalization analyses results suggest that FCRL3, FADS1, and FADS2 are shared genes associated with both vitiligo and RA." (PMID 40468464, 2025). "In SMR analyses and colocalization analyses, we identified three shared genes associated with both vitiligo and RA, including: FCRL3, FADS1, and FADS2." (PMID 40468464, 2025). "RT-qPCR was used to verify that FADS1 expression was lower in vitiligo-affected tissues and vitiligo melanocyte PIG3V cells than in matched controls or normal human epidermal PIG1 melanocytes." (PMID 31866583, 2019). "Our study shows that FADS1 downregulation in normal epidermal cells reproduces the mitochondrial deficits found in vitiligo melanocytes, namely increased ROS generation, decreased MMP, and induction of the mitochondrial-mediated apoptosis pathway." (PMID 31866583, 2019). "We found that compared with adjacent normal controls, vitiligo clinical specimens exhibit significant downregulation of fatty acid desaturase 1 (FADS1), a member of the fatty acid desaturase gene family located along with FADS2 at locus 11q12-13.1." (PMID 31866583, 2019). "In summary, we observed that FADS1 is downregulated in both clinical vitiligo samples and immortalized PIG3V human vitiligo melanocytes, where forced FADS1 expression stimulates cell growth." (PMID 31866583, 2019). "We found that FADS1 was downregulated in both human vitiligo samples and vitiligo PIG3V melanocytes as to compared to matched normal skin or normal epidermal PIG1 melanocytes." (PMID 31866583, 2019). "Because we found that the fatty acid desaturase 1 (FADS1) gene was downregulated in vitiligo specimens, we carried out experiments to assess its role in melanocyte replication and survival." (PMID 31866583, 2019). "In the present study, we investigated the effects of FADS1 expression on proliferation, apoptosis, and markers of mitochondrial oxidative stress in normal and vitiligo melanocytes." (PMID 31866583, 2019). "Additionally, we detected potential shared susceptibility genes between vitiligo and RA through SMR analyses, namely FCRL3, FADS1, and FADS3." (PMID 40468464, 2025). "Our study suggests that downregulation of FADS1 in vitiligo melanocytes could be a critical determinant for apoptosis, since its suppression in normal PIG1 cells triggers apoptosis by increasing ROS generation as well as expression of Bax and active caspases 3 and 9, while downregulating Bcl-2." (PMID 31866583, 2019). "The eQTL data of FCRL3, FADS1, and FADS2 were analyzed for colocalization with GWAS data for both vitiligo and RA." (PMID 40468464, 2025). "However, whether FADS1 dysregulation contributes to vitiligo remains uncertain." (PMID 31866583, 2019). "We also used qRT-PCR to detect the expression of FADS1 in two human epidermal cell lines, namely PIG3V vitiligo melanocytes and normal PIG1 melanocytes." (PMID 31866583, 2019).
acne (1 paper, 2024). An inflammatory process of the sebaceous glands which is characterized by comedones, nodules, papules and/or pustules on the skin. "Two novel acne associated loci, identified in this study, contain genes encoding enzymes involved in lipid metabolism: FADS1/FADS2 and FASN." (PMID 36922633, 2024).
Allergy (1 paper, 2019). An allergy is an immune response or reaction to substances that are usually not harmful. "We investigated whether DNA-M and expression of the FADS1/2 and ELOVL5 genes were associated with allergy in children and gestational fish intake." (PMID 31244960, 2019). "The association between induced FADS1/2 and ELOVL5 DNA-M and reduced gene expression due to gestational fish intake provide a mechanistic explanation of the previously observed association between maternal LCPUFA intake and allergy development in early childhood." (PMID 31244960, 2019).
anorexia nervosa (1 paper, 2022). A disorder most often seen in adolescent females characterized by a refusal to maintain a minimally normal body weight, an intense fear of gaining weight, a disturbance in body image, and, in postmenarcheal females, the development of amenorrhea. "There were also several other nominal associations (p < 0.05), including one of particular interest in the case of the BIP FADS1 network PES, for which a higher score displayed some evidence of a protective effect on self-reported anorexia nervosa." (PMID 36055211, 2022).
brain tumor (1 paper, 2022). "Interestingly, all brain tumor types demonstrated a negative correlation between FADS1 expression and patient survival." (PMID 36046053, 2022).
chronic periodontitis (1 paper, 2024). A chronic inflammatory process that affects the tissues that surround and support the teeth. "This study aims to analyze the association between FADS1 gene polymorphism and various stages of periodontitis." (PMID 39070486, 2024). "Periodontal disease treatment strategies can be based on this, which can provide compelling evidence of a link between periodontitis and the FADS1 gene polymorphism." (PMID 39070486, 2024). "FADS1 (fatty acid desaturase 1) gene polymorphism results in more susceptibility to certain metabolic diseases and chronic inflammatory diseases like periodontitis." (PMID 39070486, 2024). "This study aimed to examine the association between FADS1 gene polymorphism and various stages of periodontitis." (PMID 39070486, 2024). "Studies investigating the connection between FADS1 and susceptibility to periodontitis are scarce." (PMID 39070486, 2024). "The amount of total cholesterol and high-density lipoprotein are influenced by FADS1 and FADS2 genes, which leads to more susceptible metabolic and chronic inflammatory diseases like periodontitis." (PMID 39070486, 2024). "Therefore, future research should concentrate on determining the expression of the FADS1 gene in the gingiva to gather additional evidence supporting the hypothesis that any genetic variation or mutation in the FADS1 receptors is linked to periodontitis." (PMID 39070486, 2024). "Although some literature has mentioned it, the relationship between FADS1 gene polymorphism and periodontitis has not been extensively explored." (PMID 39070486, 2024). "However, the FADS1 gene and chronic periodontitis did not significantly correlate in the current study." (PMID 39070486, 2024).
cognitive decline (1 paper, 2020). "The present study lends further support to this hypothesis by highlighting the potential role of the FADS1 SNP in age-related vision and cognitive decline." (PMID 33178008, 2020).
Cognitive impairment (1 paper, 2020). Abnormal cognition is characterized by deficits in thinking, reasoning, or remembering. "All 12 of those scoring positive for cognitive impairment on the MoCA were carriers of the FADS1 SNP." (PMID 33178008, 2020). "The results suggest that the FADS1 SNP may play a role in visual impairment/cognitive impairment comorbidity as reflected in the poorer cognitive scores among homozygotes with AMD compared to those carrying only one, or no copies of the SNP." (PMID 33178008, 2020).
colon adenoma (1 paper, 2023). An adenoma that arises from the colon. "The protein expression of FADS1 also gradually increased during the progression of CRC from normal tissue to colon adenoma to CRC." (PMID 37041160, 2023). "The mRNA expression of FADS1 exhibited an increasing trend from colon normal tissue to colon adenoma to CRC, but this was not true for other enzymes." (PMID 37041160, 2023).
colorectal polyp (1 paper, 2024). "We report that the FADS Indel, a functional 22 bp insertion-deletion polymorphism in FADS2 (rs66698963), which is known to direct FADS1-dependent synthesis and availability of the n–6 HUFA AA, stratifies participants in the seAFOod trial that display colorectal polyp prevention by the n–3 HUFA EPA." (PMID 38879016, 2024).
eczema (1 paper, 2010). "Association of FADS1 FADS 2 variants with parental reported eczema." (PMID 20948998, 2010). "With data on variants of the FADS1 FADS2 gene cluster, PUFA and information on eczema status within the first 2 years of life for more than 800 children this is a large study despite the potential lack of power to detect small effects regarding eczema." (PMID 20948998, 2010). "Of all analyzed indicator coded SNPs of the FADS1 FADS2 gene cluster none showed a statistically significant association with the dichotomous outcome parental reported eczema in the first 2 years of life in both unadjusted and adjusted analyses." (PMID 20948998, 2010).
endometriosis (1 paper, 2025). The growth of functional endometrial tissue in anatomic sites outside the uterine body. "MR analysis suggested that, as the expression levels of FADS1 and MGRN1increase, the risk of developing endometriosis rises." (PMID 40140093, 2025). "Therefore, the function or gene polymorphisms of FADS1 may indirectly influence the development and severity of endometriosis by affecting these metabolic pathways." (PMID 40140093, 2025). "Although there is no direct link between FADS1 and endometriosis, ω−6 fatty acids are generally considered to promote inflammatory responses, while ω−3fatty acids have anti-inflammatory effects (Simopoulos 2002, Omega-6 2024)." (PMID 40140093, 2025).
endothelial dysfunction (1 paper, 2025). In vascular diseases, endothelial dysfunction is a systemic pathological state of the endothelium (the inner lining of blood vessels) and can be broadly defined as an imbalance between vasodilating and vasoconstricting substances produced by (or acting on) the endothelium. "The observed alterations in lipid metabolism can be attributed to the upregulation of stearoyl-CoA desaturase-1 (SCD1) and the impairment of FADS1/2 and ELOVL2/5 activity, which in turn give rise to conditions conducive to inflammation, endothelial dysfunction, and plaque instability." (PMID 40564102, 2025).
Failure to thrive (1 paper, 2017). Failure to thrive (FTT) refers to a child whose physical growth is substantially below the norm. "FADS1 deficiency in mice leads to the synthesis of arachidonic acid-derived eicosanoids, which results in failure to thrive and death by 12 weeks of age." (PMID 28606124, 2017).
Familial adenomatous polyposis (1 paper, 2025). Familial adenomatous polyposis (FAP) is characterized by the development of hundreds to thousands of adenomas in the rectum and colon during the second decade of life. "A recent meta-analysis reported that higher serum ALA levels were significantly associated with a reduced CRC risk, and EPA has been shown to downregulate FADS1 expression, with evidence of chemopreventive effects in patients with familial adenomatous polyposis." (PMID 41153716, 2025).
gallstones (1 paper, 2020). Solid crystalline precipitates in the biliary tract, usually formed in the gallbladder, resulting in the condition of cholelithiasis. "Previously reported FADS1/2 associations are with all lipid traits (TG lead trait, P = 7.0e-38) in GLGC data and with metabolite measurements and gallstones in the GWAS catalog." (PMID 32499813, 2020).
hepatitis B (1 paper, 2018). "The reduced level of PUFA (n-3, n-6), is possibly due to lower activities of ∆ 5 desaturase and ∆ 6 desaturase enzymes and higher activity of ∆ 9 desaturase in hepatitis B patients that enumerate impair activity of FADS1 and FADS2." (PMID 29506525, 2018).
hepatoma (1 paper, 2021). "An in vitro study demonstrated that the relative mRNA expressions of FADS2 (D6D) and FADS1 (D5D) genes were lower in vitamin B6-restricted human hepatoma cells than in control." (PMID 33572554, 2021).
keloid (1 paper, 2023). An irregularly shaped, elevated mark on the skin caused by deposits of excessive amounts of collagen during wound healing. "In another study, the expression of fatty acid desaturase 1 and 2 (FAD1 and FAD2)—key enzymes in the polyunsaturated fatty acids (PUFAs) metabolism with demonstrated anti-inflammatory function —were lower in keloids and keloid-derived fibroblasts." (PMID 36899815, 2023).
large cell lymphomas (1 paper, 2024). "Both expression and metabolic activity of fatty acid desaturase 1 (FADS1) and FADS2 which synthesized AA from the precursor was not altered, suggesting that PUFA synthesis is unlikely to be involved in AA reduction in EBV-infected large cell lymphomas (LCLs)." (PMID 38719806, 2024).
leprosy (1 paper, 2024). Leprosy is a chronic infectious disease affecting primarily the skin and peripheral nervous system. "In the E-MTAB-10318 dataset, APOE, CYP27A1, FADS1, and SOAT1 showed higher expression levels in leprosy compared to the control group." (PMID 38273053, 2024).
leukemia (1 paper, 2024). A malignant (clonal) hematologic disorder, involving hematopoietic stem cells and characterized by the presence of primitive or atypical myeloid or lymphoid cells in the bone marrow and the blood. "We next assessed how Fads1 inhibition impacted the ability of MLL-AF9 cells to induce leukemia in syngeneic mice." (PMID 38522521, 2024). "Similar to our observations in mouse leukemia cells, inducible expression of FADS1-targeting shRNAs (i-shFADS1.1 or i-shFADS1.2) impeded the growth of human AML cell lines expressing MLL-AF9 (NOMO1 and MOLM14) as well as that of a normal-karyotype AMLcell line, OCI-AML3." (PMID 38522521, 2024). "Functionally, shRNA-mediated inhibition of FADS1 reduced AML cell growth in vitro and significantly delayed leukemia onset in an AML mouse model." (PMID 38522521, 2024). "In two other AML patient cohorts, we found that FADS1 mRNA is elevated across multiple AML subtypes compared to healthy controls and is particularly high in mixed lineage leuekmia (MLL) (also known as KMT2A)-rearranged leukemia." (PMID 38522521, 2024).
liver cancer (1 paper, 2022). An epithelial or non-epithelial malignant neoplasm that arises from the liver. "After evaluating the correlation of these fatty acid‐related genes with the ES cell‐like gene expression signatures in HCC, we found that four genes, including ACSL3, ACSL4, FADS1, and FADS2, were highly related to stem cell characteristics in liver cancer." (PMID 35603967, 2022).
liver disease (1 paper, 2025). "Older adults, patients with liver disease, or those with FADS1/2 mutations have a low ability to convert to ALA." (PMID 40521363, 2025).
lymph node metastasis (1 paper, 2023). "FADS1/4 expression was obviously lower in BC patients with higher lymph node metastasis than lower lymph node metastasis, while FADS7/8 expression was obviously higher in BC patients with higher lymph node metastasis than lower lymph node metastasis." (PMID 37122728, 2023).
mood disorder (1 paper, 2023). A cognitive disorder a disturbance in which the person's mood is hypothesized to be the main underlying feature. "These enzymes (FADS1 and FADS2) are involved in the metabolism of eicosapentaenoic acid (EPA) and docosahexaenoic acid (DHA), which are thought to potentially benefit patients with mood disorders." (PMID 36806390, 2023).
myeloma (1 paper, 2020). "Like our data from analysis of normal donor versus myeloma patient MSCs, we again found that Fads1 and Fads2 were significantly downregulated in MM-3T3-L1s compared to controls." (PMID 33680918, 2020).
myopia (1 paper, 2025). "After colocalization analysis, we discovered compelling evidence indicating that genetically predicted elevated levels of the FADS1 gene in the retina were linked to reduced risks of high myopia, showing the high tissue specificity of colocalization." (PMID 40792044, 2025). "Although SMR identified associations between the FADS1 gene and three myopia traits, strong evidence for colocalization was found only for the relationship between the FADS1 gene expressing in the retina and high myopia." (PMID 40792044, 2025). "Our MR study indicated that omega‐3 PUFAs were found to be associated with myopia in European populations, and identified an association between the expression of FADS1 gene in retina and high myopia." (PMID 40792044, 2025). "SMR analysis identified associations between the FADS1 gene and three myopia traits." (PMID 40792044, 2025). "In secondary analysis for MR, we found that potential associations between omega‐3 PUFAs and three traits of myopia were almost driven by SNPs within the FADS region, especially the FADS1 region." (PMID 40792044, 2025). "Summary data‐based Mendelian randomization (SMR) and colocalization analysis were conducted to examine the associations between the FADS1 and FADS2 genes and three traits of myopia in European populations." (PMID 40792044, 2025). "However, only the associations between the expression of FADS1 in both blood and retinal tissues and the trait of myopia, as well as the association between FADS1 expression in retinal tissue and the traits of RSE and high myopia, passed the HEIDI test (p > 0.05)." (PMID 40792044, 2025).
neuroblastoma (1 paper, 2020). Neuroblastoma (NB) is the most common solid, extracranial childhood tumor. "The increased expression of FADS1 in the peritumoral area in women could be attributed to the influence of estradiol, which increased the expression of FADS1 in human neuroblastoma SH-SY5Y cells." (PMID 32392704, 2020).
prostate adenocarcinoma (1 paper, 2022). "After bonferroni-correction (P<7.05×10-5), 81 SNPs were signficantly associated with FADS1 mRNA exression mainly among 5 cancer types: CESC, LGG, LIHC, prostate adenocarcinoma (PRAD) and STAD." (PMID 36046053, 2022).
subarachnoid hemorrhage (1 paper, 2019). A serious neurological disorder characterized by intracranial hemorrhage into the subarachnoid space. "However, only a significant association between DHA and subarachnoid hemorrhage was still obtained when SNPs in or close to the FADS1 gene (rs174547, rs174538, and rs102275) were not included in the analysis." (PMID 31817859, 2019).
triple-negative breast carcinoma (1 paper, 2025). An invasive breast carcinoma which is negative for expression of estrogen receptor (ER), progesterone receptor (PR), and human epidermal growth factor receptor 2 (HER2). "In triple-negative breast cancer, TNBC with high FADS1/2 expression were found to be highly sensitive to ferroptosis and inhibition of FADS1/2 expression decreased the ratio of polyunsaturated fatty acids and inhibited ferroptosis." (PMID 40535804, 2025).
type-1 diabetes (1 paper, 2021). "FADS1 has been reported to play a crucial role in many diseases, including type-1 diabetes and cancer." (PMID 34706720, 2021).